KCNAB3 (potassium voltage-gated channel subfamily A regulatory beta subunit 3)
Description:
Regulatory subunit of the voltage-gated potassium (Kv) channels composed of pore-forming and potassium-conducting alpha subunits and of regulatory beta subunit. The beta-3/KCNAB3 subunit may mediate closure of potassium channels (By similarity). Increases inactivation of Kv1.5/KCNA5 alpha subunit-containing channels. May display nicotinamide adenine dinucleotide phosphate (NADPH)-dependent aldoketoreductase activity (By similarity). The binding of oxidized and reduced NADP(H) cofactors may be required for the regulation of potassium channel activity (By similarity).
Synonyms: KCNA3B; AKR6A9; KCNA3.1B; KV-BETA-3
Tractability: Antibody: its Gene Ontology location is reachable by antibodies, with high confidence. PROTAC: ubiquitination databases record sites on it.
Gene: Protein-coding gene on chromosome 17 (7,921,577 to 7,929,856, reverse strand). Ensembl gene ENSG00000170049.
Subcellular location: Cytoplasm
Subcellular location (Human Protein Atlas): Mitochondria
Pathways (Reactome):
Neuronal System: Voltage gated Potassium channels
Gene Ontology:
Molecular function: protein binding; alcohol dehydrogenase (NADP+) activity; potassium channel regulator activity; transmembrane transporter binding; voltage-gated potassium channel activity
Biological process: potassium ion transport; regulation of potassium ion transmembrane transport; potassium ion transmembrane transport
Cellular component: cytoplasm; plasma membrane; voltage-gated potassium channel complex; membrane
Genetic constraint (gnomAD): Loss-of-function variants: 62 observed, 65.93 expected, observed/expected ratio (o/e) 0.94, 90% interval 0.77 to 1.16. The upper end of that interval is the gene's LOEUF score, 1.16, which puts it in group 5 of 6, group 1 being the genes least tolerant of losing a copy. Missense variants: 514 observed, 525.98 expected, observed/expected ratio (o/e) 0.98, 90% interval 0.91 to 1.05. Synonymous variants: 212 observed, 205.65 expected, observed/expected ratio (o/e) 1.03, 90% interval 0.92 to 1.15.
Homologues: Orthologues: chimpanzee KCNAB3 (99% identical), macaque KCNAB3 (99% identical), dog KCNAB3 (97% identical), guinea pig KCNAB3 (96% identical), mouse Kcnab3 (93% identical), rat Kcnab3 (92% identical), rabbit KCNAB3 (91% identical), pig KCNAB3 (77% identical), tropical clawed frog kcnab3 (73% identical), zebrafish KCNAB3 (58% identical), Caenorhabditis elegans Y39G8B.1 (18% identical), Caenorhabditis elegans C01G5.5 (15% identical), and 3 more. Paralogues in human: KCNAB2 (64% identical), KCNAB1 (64% identical), AKR1C2 (21% identical), AKR1C4 (21% identical), AKR1C1 (21% identical), AKR1C3 (21% identical), AKR7A2 (20% identical), AKR1B1 (20% identical), AKR1D1 (20% identical), AKR1C8 (19% identical), AKR1B10 (19% identical), AKR7A3 (19% identical), and 4 more.
Diseases named in the same sentence as KCNAB3 in open-access papers:
KCNAB3 is named in the same sentence as 11 diseases in open-access papers, as found by Europe PMC text mining. Sharing a sentence is not in itself a finding about the gene and the disease. The quoted sentences say what the papers report.
schizophrenia (2 papers, 2015 to 2024). A major psychotic disorder characterized by abnormalities in the perception or expression of reality. "The identification of a novel DMR associated with schizophrenia mapping to KCNAB3, a gene coding subunit of voltage-gated potassium ion channel, may also have the potential as a drug target." (PMID 38503926, 2024). "The HTR2A gene codes for a serotonin receptor and is associated with behavioral traits, schizophrenia and depression, KCNAB3 encodes a subunit of a voltage-sensitive potassium channel, and SPNS1 codes for the Spinster-1 protein implicated in apoptosis in the Drosophila central nervous system." (PMID 26607552, 2015). "DNA methylation changes at COMT and KCNAB3 may be one of the pathways involved in the pathophysiology of schizophrenia at least in a subgroup of patients although this needs further research." (PMID 38503926, 2024).
autism (1 paper, 2022). Persistent deficits in social interaction and communication and interaction as well as a markedly restricted repertoire of activity and interest as well as repetitive patterns of behavior. "We hypothesize that genes severely dysregulated in autism such as SCN1B, KCNAB3, FMN1, or VAMP1 might additionally contribute to the excitation-to-inhibition ratio affecting normal network function and circuitry." (PMID 35680911, 2022).
channelopathy (1 paper, 2025). Channelopathies are a group of diseases caused by the dysfunction of ion channel subunits or their interacting proteins. "Studying the role of KCNAB3 in SMS-associated channelopathy, such as blocking Kv1 channels and interrupting Kvβ3- Kvα interaction in SMS neurons, can be a future direction." (PMID 40882620, 2025).
hemorrhagic disease (1 paper, 2021). Spontaneous or near spontaneous bleeding caused by a defect in clotting mechanisms (blood coagulation disorders) or another abnormality causing a structural flaw in the blood vessels (hemostatic disorders). "Most of these genes are known to be involved in the manifestation of various clinical phenotypes, such as metabolic diseases (CPT1B and BLVRA); hemorrhagic diseases (RUNX1 and GP6); and neuronal disorders (KCNAB3, FAM179B, CCDC60, GRM6, and PRDM8), among others." (PMID 34440289, 2021).
hidradenitis suppurativa (1 paper, 2025). A chronic suppurative and cicatricial disease of the apocrine glands occurring chiefly in the axillae in women and in the groin and anal regions in men. "Potassium channels: Pain perception in hidradenitis suppurativa may be significantly influenced by the dysregulation of potassium channels, including genes such as KCNMA1, KCNQ5, KCNB2, KCND2, KCND3, and KCNAB3, all of which were identified in this study." (PMID 39940809, 2025).
liver dysfunction (1 paper, 2019). "KCNAB3 was found to be significantly higher in the AR group compared with the group with liver dysfunction and no AR (+LR 2.25; –LR 0.17)." (PMID 31031758, 2019).
migraine (1 paper, 2020). "Researchers have reported (Lafrenière & Rouleau, 2012) that the KCNAB3 gene may be associated with severe migraine, but the mutation site has not been clearly reported; therefore, the relationship between this gene and human neurological diseases needs to be further explored." (PMID 32990398, 2020).
cancer (3 papers, 2017 to 2022). A tumor composed of atypical neoplastic, often pleomorphic cells that invade other tissues. "The actual role of KCNAB3 hypermethylation remains unclear, and a genome-wide analysis revealed hypermethylation in KCNAB3 in pre-cancer, suggesting that this alteration is a positive driver for oncogenesis." (PMID 35008848, 2021). "The eight cross-cancer CpGs were annotated to genes involved in transport (KCNA3, KCNAB3 and TRAPPC1), signal transduction (AGAP3 and LIME1), microtubule assembly (FES and SHROOM1), and metal binding (FURIN and AGAP3)." (PMID 35710732, 2022). "Hypermethylation has already been reported for PAX5, KCNAB3, MEIS2 and GFRA3 in different cancer entities." (PMID 28634396, 2017).
KCNAB3 also shares sentences with these, for which no sentence is quoted: depression (1 paper); metabolic disease (1); neurological diseases (1).